RAG1 (recombination activating 1)
Diseases named in the same sentence as RAG1 in open-access papers (continued):
Sharing a sentence is not in itself a finding about the gene and the disease.
myeloma (6 papers, 1992 to 2022). "For in vivo studies, we used Rag1-deficient mice as recipients of PD-1+ T cell adoptive therapy to assess anti-myeloma efficacy." (PMID 28642819, 2017). "Rag1-deficient mice were used as immunotherapy recipients as they provided a ‘clean’ system to assess the anti-myeloma effects provided by adoptively transferred T cells." (PMID 28642819, 2017). "All 6 young Rag1-deficient C57BL/6 mice given 3 million purified splenic T cells from young wild-type C57BL/6 mice 1 week before the injection of 10 million 5T33L myeloma cells were protected from the growth of 5T33L MMM cells." (PMID 23419047, 2013). "Rag-1-deficient mice were inoculated with 106 5T33-GFP myeloma cells iv." (PMID 28642819, 2017). "Furthermore, the proliferation of 5T33L myeloma cells in Rag1-deficient C57BL/6 mice was greater in mice which also received spleen T cells from 18–20 month old C57BL/6 wild-type mice compared to mice which received splenic T cells from 3–4 month old C57BL/6 wild-type mice." (PMID 23419047, 2013). "Stable hybrids between the scid pre-B and the myeloma cells had lost theexpression of RAG-1 and RAG-2 genes, supporting the previous finding of an inhibitorof rearrangement in myeloma cells that acts shortly after fusion." (PMID 1343097, 1992). "To extend these observations to an animal model of human myeloma, we transferred ARP1OE and ARP1EV cells to immunodeficient NOD.Cγ Rag1 mice." (PMID 25230277, 2014).
T cell deficiency (6 papers, 2017 to 2022). "This study addresses the functional role of lymphocytes in prostate cancer development using a genetically engineered mouse model (GEMM) of human c-Myc driven prostate cancer (Hi-Myc mice) combined with B and T cell deficiency (RAG1-/- mice)." (PMID 29212195, 2017). "To identify potential responsible molecular etiologies underlying CD4+ T cell deficiency-mediated LGG formation, we performed transcriptomal analysis on whole brainstems of wild type and Rag1−/− mice." (PMID 35986378, 2022).
chronic granulomatous disease (5 papers, 2019 to 2026). Chronic granulomatous disease (CGD) is a rare primary immunodeficiency, mainly affecting phagocytes, which is characterized by an increased susceptibility to severe and recurrent bacterial and fungal infections, along with the development of granulomas. "Out of 107 patients, eight died (8/107, 7.5%); six of these deaths occurred in patients with chronic granulomatous disease (CGD) and two in patients with RAG1 deficiency." (PMID 41528247, 2026). "Similar to SCIDs, other types of PIDs that can be treated by allo-HSCT are in principle eligible for autologous HSCs gene therapy, such as Wiskott-Aldrich syndrome (WAS), chronic granulomatous disease (CGD), recombination activating gene severe combined immunodeficiency (RAG1, RAG2) and so on." (PMID 35782737, 2022).
colorectal cancer (5 papers, 2021 to 2023). A primary or metastatic malignant neoplasm that affects the colon or rectum. "To this end, we generated subcutaneous MC38 murine colorectal carcinoma syngeneic xenografts in wild-type (C57BL/6) mice, T and B cell-deficient Rag1−/− mice and severely immunocompromised Rag2−/−γc−/− mice, which lack both adaptive and innate lymphoid cells, and compared the tumour growth rates." (PMID 33535624, 2021). "Growth of the human HT-29 colorectal cancer cell line was evaluated after subcutaneous inoculation in AlbuMus RAG1 KO and compared to the C57BL/6 RAG1 KO strain." (PMID 33686177, 2021). "Additionally, in vivo studies using adoptive transfer in appropriate mouse models, such as Rag1-/-mice, could elucidate the effect of MCC on CD4+ T cell differentiation in the context of colorectal cancer genesis and development." (PMID 37569317, 2023).
lupus (5 papers, 2013 to 2023). "To explore the role of lymphocytes in the progression of lupus IgG-induced liver damage, we used RAG-1-deficient mice that lack mature T and B cells." (PMID 29988500, 2018). "Lupus-prone mice (TC), TC.Rag1-/- mice that lack B and T cells, and congenic B6 healthy controls were treated with R848." (PMID 37483626, 2023). "To examine specific functional effects of Fli1+/- compared to Fli1+/+ lupus T cells, we performed an adoptive transfer experiment using Rag1-/- mice as recipients." (PMID 24040398, 2013). "The phylogenetic tree also evidenced the recovery of two species complexes (those of pricei and lupus) and supported the position of Ictalurus dugesii as the sister taxon of the pricei complex, as suggested by analysis of the independent genes coxI, and RAG1." (PMID 37370016, 2023). "We found that the severity of liver inflammation and changes in the liver enzymes induced by lupus IgG were not significantly decreased in RAG-1-deficient mice compared with those in wild-type mice." (PMID 29988500, 2018). "Moreover, for the nuclear gene RAG1, the lack of resolution in the more derived groups, as was the case with the pricei and lupus complexes, could be associated with incomplete lineage sorting from this nuclear gene." (PMID 37370016, 2023).
ZIKV infection (5 papers, 2018 to 2025). "Intracranial ZIKV infection in C57BL/6 WT or Rag1-/- mice (deficient in mature T and B cells) resulted in lethal encephalitis with infiltration of macrophages and NK cells." (PMID 35747137, 2022). "Thus, we treated Rag1−/− mice, which are deficient in T- and B-cells, with anti-IFNAR1 blocking antibody that inhibits signaling through the IFN-α/β receptor (subsequently called AIR mice) to reduce their resistance to ZIKV infection." (PMID 35379362, 2022). "Thus, Rag1−/− mice could be ideal to study postnatal ZIKV infection and pathogenesis, as Rag1 does not influence fetal or postnatal brain development." (PMID 35379362, 2022). "Further, in line with a minor role for T and B cells following intracranial ZIKV infection, we observed only slight differences in the clinical course and somewhat more widespread infection in the CNS—in the absence of overall increased virus RNA levels—in Rag1−/− mice compared with WT mice." (PMID 31511023, 2019).
agammaglobulinemia (4 papers, 2015 to 2025). A decreased level of serum immunoglobulins. "By NGS it is possible to identify unexpected mutations in apparently not corresponding PID cases, as recently reported by our group for a patient with agammaglobulinemia due to RAG1 deficiency." (PMID 31031743, 2019). "We report herein a novel presentation of leaky RAG1/RAG2 deficiency which is associated with selective IgG antibody deficiency and massively decreased numbers of naïve CD4+ T-cells." (PMID 26186701, 2015). "Hypomorphic mutations in other IEI genes (BTK, GATA2, IL2RG, JAK3, RAG1, RAG2, etc.)have been previously found in patients with antibody deficiency and milder phenotypes or in CVID patients." (PMID 34975878, 2021). "Moreover, the spectrum of genetic variants identified in our patients—including TNFRSF13B, DOCK8, RAG1, and LRBA—closely resembles the mutational landscape reported in prior studies of CVID and other antibody deficiencies." (PMID 40993545, 2025). "Pathogenic variants in CTLA4, LRBA, TNFRSF13B (TACI), DOCK8, RAG1, PRF1, PIK3CD, IKZF1, and PRKDC have been identified in patients with AICs and PIDs, often associated with other clinical features such as lymphoproliferation, splenomegaly, and immunologic abnormalities such as hypogammaglobulinemia." (PMID 40993545, 2025).
B cell lymphoma (4 papers, 2016 to 2024). "The present study shows that PFOA, PFOS, PFNA and PFHxS cause a time- and concentration-dependent downregulation of RAG1 and RAG2 gene expression in the human B cell lymphoma Namalwa cell line." (PMID 36326898, 2022). "To study the effect of anti-SLAMF6 on tumor progression we use the aggressive transplantable murine CLL clone TCL1-192 and the B cell lymphoma LMP2A/λMyc into SCID or Rag1−/− mice, respectively." (PMID 27029059, 2016).
COVID-19 (4 papers, 2021 to 2024). A disease caused by infection with severe acute respiratory syndrome coronavirus 2. "On the other hand, a higher COVID-19 mortality rate in specific monogenic DNA repair defects (such as RAG1/RAG2, DNMT3B deficiencies) exists based on the current observation." (PMID 35713311, 2022). "Here, we develop and validate a high throughput extension of PhIP-seq in various etiologies of autoimmune and inflammatory diseases, including APS1, IPEX, RAG1/2 deficiency, Kawasaki disease (KD), multisystem inflammatory syndrome in children (MIS-C), and finally, mild and severe forms of COVID-19." (PMID 36300623, 2022).
lung carcinoma (4 papers, 2015 to 2025). "To investigate the molecular causes that led to high incidence of lung carcinomas in RAG1−/− Sgo1−/+ mice, we performed RNAseq-transcriptome analyses using normal-looking lung tissues from RAG1−/− (N=3) and RAG1−/− Sgo1−/+ (N=3) mice." (PMID 27526110, 2016). "Six among the 10 surviving RAG1−/− Sgo1−/+ mice (37.5%) had gross lung carcinomas at the 12 months end point." (PMID 27526110, 2016). "As lung carcinomas preferentially developed on the RAG1−/− background, we hypothesized that adoptive immunity is involved in suppressing CIN cells in the lung, and that genes or proteins involved in the immune system would be misregulated in Sgo1." (PMID 27526110, 2016). "To investigate the expression of E-cadherin in lung dendritic cells in the presence of different immune responses, we harvested lung tissue from the Lewis orthotopic lung cancer model, C57BL/6, Rag1 KO mice and Rag1 KO mice exposed to an anti-CD40 antibody, respectively." (PMID 25651850, 2015).
lung disease (4 papers, 2021 to 2025). "Indeed, Rag1−/− mice, which lack B and T cells, show less lung disease after SARS-CoV infection than wild-type mice." (PMID 38337035, 2024). "Lung disease in the N153S mice appeared to be T-cell-mediated, since Rag1−/− STING N153S mice, which lack T cells and mature B cells, exhibited no histological evidence of lung disease and Tcrβ−/− STING N153S mice developed only very mild lung disease." (PMID 35159128, 2022).
lung fibrosis (4 papers, 2012 to 2024). "Hams and colleagues showed that antibody‐mediated depletion of ILC2 cells in lymphocyte‐deficient Rag1‐/‐ mice could reduce the size of S. mansoni egg‐induced granulomas and the degree of pulmonary fibrosis." (PMID 32742653, 2020). "Furthermore, exogenous administration of IL-6 family cytokines may short-circuit the need for lymphocytes, because in their absence in Rag1−/− mice, Osm can promote lung fibrosis." (PMID 22684844, 2012). "In contrast, when Hps1−/− mice were bred with Rag1−/− mice to deplete T cells, Hps1−/−Rag1−/− double-mutant mice were not protected from bleomycin-induced lung fibrosis development, suggesting Th2s did not contribute to fibrosis development in this model." (PMID 39405112, 2024). "However, FITC‐treated T‐cell‐depleted SCID and Rag1‐/‐ mice still developed lung fibrosis suggesting that the adaptive immune system is not involved in fibrogenesis in these animals." (PMID 32742653, 2020).
parasitemia (4 papers, 2015 to 2024). "B and T cell deficient rag1-/- and rag1-/-/ inos-/- mice showed similar body weight loss and parasitemia levels after infection." (PMID 26915097, 2016). "NK T cells (still present in Rag-1-/- mice) also produce IL-4 in response to certain parasitic infections." (PMID 39083533, 2024). "Rag1-/- mice reconstituted with CD4 T cells showed similar parasitemia titers, but increased levels of ifng, inos and tnf mRNA as compared to non-transferred infected controls." (PMID 34587172, 2021). "Rag1-/- mice showed higher parasitemia levels than WT mice and increased cumulative mortality (p<0.05, χ2 test), without a significant weight loss." (PMID 34587172, 2021). "Thin blood smears from recipient mice identified that following infection of Rag1–/–mice, very high parasitemia is observed." (PMID 26147567, 2015). "The adoptive transfer of naïve T cells to Rag1–/–mice significantly reduced the high parasitemia, confirming an important T cell-dependent role in the control of high parasitemia during acute infection." (PMID 26147567, 2015). "However, Il4gfp+ Th2 cells transferred to MHC Class II-deficient Rag1–/–recipient mice remained Il4gfp+, did not express Ifngyfp and failed to reduce severe parasitemia." (PMID 26147567, 2015).
thymic lymphoma (4 papers, 2012 to 2025). "C8, C11, C7, and C18 were proximal to double‐positive T cells, representing thymic lymphoma characterised by elevated expression levels of genes like Notch1, Hes1 and Desi1,72, 73 along with markers associated with thymic T‐cell development such as Rag1/2, Xrcc6 and Dntt74." (PMID 40887856, 2025).
AIDS (3 papers, 2015 to 2024). A syndrome resulting from the acquired deficiency of cellular immunity caused by the human immunodeficiency virus (HIV). "This is supported by the extreme susceptibility of Ifng-/- and Rag1-/- mice, the high co-morbidity between TB and low CD4 T cell counts caused by AIDS, and the ability of recombinant IFN-γ to control bacterial growth in mouse and human macrophages in vitro." (PMID 35877763, 2022). "Since the majority of E. africanus cases are diagnosed in patients with advanced HIV disease (AIDS) and thus very low CD4+ T-lymphocyte counts, a Rag-1-deficient (devoid of mature T and B lymphocytes) murine model of infection was established to study the infection in an immunocompromised host." (PMID 38198478, 2024). "Those with HIV/AIDS could also conceivably have the granulomatous-type inflammation seen in persistently infected RAG1-/- mice." (PMID 26115459, 2015). "Though the viremia seen in RAG1-/- mice is too low for mosquito transmission, more study needs to be done in individuals with HIV/AIDS to determine the levels of viremia and if sustained viremia occurs." (PMID 26115459, 2015).
Arthritis (3 papers, 2018 to 2022). Inflammation of a joint. "Because BCL6 plays a dominant role in T cell and B cell responses, the effect of FX1 treatment on Lyme arthritis severity was evaluated in B6 Rag1-/- mice to determine the contribution of T cells and B cells to IFNβ production and arthritis." (PMID 35324997, 2022). "However, DBA/1 mice deficient in the RAG1 gene still developed some synovial hyperplasia, pannus, and erosions of cartilage and bone, demonstrating that arthritis development is still possible even in the absence of mature T and B lymphocytes." (PMID 29495570, 2018). "Also, T and B cells are not required since arthritis developed in recombination activating gene 1 (RAG1) deficient mice but IL-17-producing T cells can augment this autoantibody-induced arthritis." (PMID 29495570, 2018). "As with B6 mice, B6 Rag1-/- mice were treated with FX1 for 11 days beginning the day before infection, and arthritis was assessed at 28 days post-infection." (PMID 35324997, 2022). "For example, the 197 TNF-Tg mouse line that was used to generate TNF-Tg/Rag1−/− mice carries multiple copies of the TNF transgene, with a very aggressive arthritis at a young age." (PMID 30510188, 2018). "FX1-treated B6 Rag1-/- mice displayed more severe Lyme arthritis than vehicle-treated control B6 Rag1-/- mice indicating that BCL6 expression in non-lymphocytes, such as myeloid cells, is critical for the increased arthritis severity observed upon FX1 treatment." (PMID 35324997, 2022).
asthma (3 papers, 2014 to 2025). "To test this, we adoptively transferred naive CD4+ T cells from DO11.10.Rag1−/− and DO11.10.Rag1−/−Cblb−/− mice into WT BALB/c recipients, and then immunized with OVA at 100 μg/ml in alum, which is the dose used to induce asthma." (PMID 24508458, 2014).
Ataxia (3 papers, 2016 to 2023). Ataxia refers to impaired coordination of voluntary muscle movement. "Interestingly, the one male Rag1-/- mouse that succumbed on day 10 was found to have ataxia and hindlimb weakness just prior to euthanasia suggesting possible neurological involvement." (PMID 33416494, 2021). "In contrast, approximately 40% of the C57BL/6 RAG1-/- mice that obtained CD4+ immune T cells developed a neurological score and the same symptoms as R. typhi-infected C57BL/6 RAG1-/- control mice including tremor and/or ataxia." (PMID 27875529, 2016).
ataxia telangiectasia (3 papers, 2013 to 2021). Ataxia-telangiectasia is the association of severe combined immunodeficiency (affecting mainly the humoral immune response) with progressive cerebellar ataxia. "The three remaining infants were diagnosed with CHARGE syndrome, ataxia telangiectasia, and SCID with homozygous RAG1 c.2974A > G SCID, one with each condition." (PMID 34287245, 2021).
dermatitis (3 papers, 2014 to 2022). An inflammatory process affecting the skin. "Through a series of experiments involving T cell transfer, generation of BM chimera, and breeding to immune deficient Rag1–/– mice, we demonstrated that the alopecia and skin inflammation are mediated by different mechanisms." (PMID 36256455, 2022). "The dermatitis seen in Sharpincpdm-Dem mice and Sharpincpdm-Dem, Rag1−/− double mutants was similar in its severity." (PMID 24465642, 2014). "The host Rag1–/– mice were grossly normal with no overt hair loss and dermatitis, regardless of reconstitution with control or Brd4fl/fl Ox40-Cre BM cells." (PMID 36256455, 2022). "Loss of lymphocytes in Sharpincpdm-Dem, Rag1−/− mice did not diminish the dermatitis consistent with the failure to induce the CPDM phenotype by hematopoietic cell transfer." (PMID 24465642, 2014). "However, the same γδ T cells transferred into unmanipulated Rag1–/– mice, which have normal healthy hair stem cells, failed to trigger dermatitis." (PMID 36256455, 2022). "However, as compared with the Brd4fl/fl Ox40-Cre mice, the hair loss in Rag1–/– CKO mice was delayed and at a slower rate, and dermatitis was absent throughout the observation time." (PMID 36256455, 2022). "Importantly, Rag1−/−Flgft/ft mice do not have lung pathology, demonstrating that the adaptive immune response is required for the progression from dermatitis to pulmonary inflammation." (PMID 26299987, 2016). "Since the Brd4fl/fl Ox40-Cre mice develop severe skin inflammation, whereas the Rag1–/– CKO mice exhibit alopecia without skin inflammation, we then examined the identity of T cells and to what extent they mediate the skin inflammation in Brd4fl/fl Ox40-Cre mice." (PMID 36256455, 2022).
experimental autoimmune encephalomyelitis (3 papers, 2011 to 2020). An autoimmune demyelinating disease of the central nervous system that is produced experimentally in animals by the injection of homogenized brain or spinal cord in Freund's adjuvant. "IFN-β-treated myelin antigen-specific Th1 cells are impaired in their ability to induce severe experimental autoimmune encephalomyelitis (EAE) upon transfer to lymphocyte-deficient Rag1-/- mice." (PMID 25885435, 2015). "Reduced Treg migration was also observed in the central nervous systems of the experimental autoimmune encephalomyelitis model Rag1 knockout mice reconstituted with bone marrow of CCR6 knockout mice." (PMID 32240221, 2020). "MACS-sorted naïve CD4+ T cells were either applied on healthy CNS slices or intravenously injected into RAG1 -/- mice, which were affected by experimental autoimmune encephalomyelitis (EAE)." (PMID 21978405, 2011).